ENSG00000212604
Synonyms: LOC124900363
Gene: Small nucleolar RNA gene on chromosome 15 (26,008,940 to 26,009,074, reverse strand). Ensembl gene ENSG00000212604.
Gene Ontology:
Biological process: RNA processing
Cellular component: nucleolus
Homologues: Paralogues in human: SNORA48 (79% identical), SNORA48B (77% identical).